SRSF3 (serine and arginine rich splicing factor 3)
Diseases named in the same sentence as SRSF3 in open-access papers (continued):
Sharing a sentence is not in itself a finding about the gene and the disease.
pneumonia (1 paper, 2024). An acute, acute and chronic, or chronic inflammation focally or diffusely affecting the lung parenchyma, caused by an infection in one or both of the lungs (by bacteria, viruses, fungi, or mycoplasma.). "In summary, N protein leads to autophagic degradation of Dicer, XPO5, SRSF3, and hnRNPA3, inducing DNA damage and proteotoxic stress and eventually causing pneumonia." (PMID 39138195, 2024). "The age-associated downregulation of Dicer, XPO5, SRSF3, and hnRNPA3 expression in lung tissues is one of the reasons why older individuals are more prone to developing severe pneumonia after SARS-CoV-2 infection than younger ones." (PMID 39138195, 2024). "Age-associated downregulation of Dicer, XPO5, SRSF3, and hnRNPA3 expression in lung tissues increases the severity of N protein-induced pneumonia." (PMID 39138195, 2024). "Here, the authors provide evidence that SARS-CoV-2 N protein leads to autophagic degradation of Dicer, XPO5, SRSF3, and hnRNPA3, inducing DNA damage and proteotoxic stress, eventually causing pneumonia." (PMID 39138195, 2024). "Therefore, age-associated downregulation of Dicer, XPO5, SRSF3, and hnRNPA3 expression in lung tissues may render older individuals more prone to developing severe pneumonia after SARS-CoV-2 infection." (PMID 39138195, 2024). "Dicer, XPO5, SRSF3, and hnRNPA3 knockdown increases, while their overexpression decreases, N protein-induced pneumonia’s severity." (PMID 39138195, 2024). "Dicer, XPO5, SRSF3, and hnRNPA3 knockdown in lung tissues led to lung injury and pneumonia, whereas their overexpression partially alleviated N protein-induced pneumonia." (PMID 39138195, 2024). "SARS-CoV-2 N protein induces the autophagic degradation of Dicer, XPO5, SRSF3, and hnRNPA3, inhibiting miRNA biogenesis and RNA splicing and triggering DNA damage, proteotoxic stress, and pneumonia." (PMID 39138195, 2024). "The effects of anastrozole on the expression of Dicer, XPO5, SRSF3, and hnRNPA3 and pneumonia were also observed in the SARS-CoV-2-infected mouse model." (PMID 39138195, 2024). "Older mice show lower expression of Dicer, XPO5, SRSF3, and hnRNPA3 in their lung tissues and exhibit more severe N protein-induced pneumonia than younger mice." (PMID 39138195, 2024). "Dicer, XPO5, SRSF3, and hnRNPA3 expression was downregulated in the lung tissues of older mice compared with that in younger mice, and N protein induced more severe lung injury and pneumonia in older mice." (PMID 39138195, 2024). "Moreover, we found that anastrozole promotes Dicer, XPO5, SRSF3, and hnRNPA3 expression and ameliorates N protein-induced pneumonia not only in young mice but also in old mice." (PMID 39138195, 2024). "Here, we show that SARS-CoV-2 N protein induces the autophagic degradation of two RNAi components (Dicer and XPO5) and two splicing factors (SRSF3 and hnRNPA3), thereby inhibiting miRNA biogenesis and RNA splicing and triggering DNA damage, proteotoxic stress, and pneumonia." (PMID 39138195, 2024). "Dicer, XPO5, SRSF3, and hnRNPA3 knockdown increased the severity of N protein-induced pneumonia." (PMID 39138195, 2024). "Moreover, genetic or pharmacological rescue of Dicer, XPO5, SRSF3, and hnRNPA3 expression relieves the N protein-induced DNA damage, proteotoxic stress, and pneumonia." (PMID 39138195, 2024). "Here, we found that anastrozole alleviated N protein- or SARS-CoV-2-induced pneumonia by promoting Dicer, XPO5, SRSF3, and hnRNPA3 expression." (PMID 39138195, 2024). "Treatment with PJ34 increased the expression of Dicer, XPO5, SRSF3, and hnRNPA3 in SARS-CoV-2-infected lung tissues and ameliorated the pneumonia induced by ectopic N protein expression and SARS-CoV-2 infection." (PMID 39138195, 2024). "Collectively, these results reveal that anastrozole alleviates SARS-CoV-2 N protein-induced pneumonia by promoting Dicer, XPO5, SRSF3, and hnRNPA3 expression." (PMID 39138195, 2024).
pneumonia (continued). "Treatment with PJ34 or anastrozole alleviates the N protein-induced DNA damage, proteotoxic stress, and pneumonia by rescuing Dicer, XPO5, SRSF3, and hnRNPA3 expression." (PMID 39138195, 2024). "Collectively, these results indicate that PJ34 alleviates pneumonia by preventing the N protein-induced downregulation of Dicer, XPO5, SRSF3, and hnRNPA3." (PMID 39138195, 2024). "PJ34, a poly(ADP-ribose) polymerase inhibitor, or anastrozole, an aromatase inhibitor, ameliorates N protein- or SARS-CoV-2-induced pneumonia by restoring Dicer, XPO5, SRSF3, and hnRNPA3 expression." (PMID 39138195, 2024). "Furthermore, SARS-CoV-2 infection also led to the downregulation of Dicer, XPO5, SRSF3, and hnRNPA3 in mouse lung tissues, and overexpression of Dicer, XPO5, SRSF3, and hnRNPA3 in mouse lung tissues partially alleviated SARS-CoV-2-induced pneumonia." (PMID 39138195, 2024). "Furthermore, Dicer, XPO5, SRSF3, and hnRNPA3 knockdown exaggerated the N protein-induced DNA damage, apoptosis, cytosolic DNA accumulation, upregulation of IFNβ, IL-6, and NKG2D ligands, and pneumonia." (PMID 39138195, 2024). "Although the expression levels of Dicer, XPO5, SRSF3, and hnRNPA3 were lower in the tissues of old mice than in those of young mice, PJ34 rescued the N-induced downregulation of Dicer, XPO5, SRSF3, and hnRNPA3 and ameliorated N protein-induced pneumonia not only in young mice but also in old mice." (PMID 39138195, 2024).
sarcoma (1 paper, 2023). A usually aggressive malignant neoplasm of the soft tissue or bone. "SRSF3 regulates multiple cancer-related genes, including EP300, DDX5, and MAP4K4, to increase the proliferation of sarcoma cells." (PMID 37558679, 2023).
soft tissue tumours (1 paper, 2022). "All 3 IVLM cases showed strong staining for SRSF3, while 77% of the other soft tissue tumours in the cohort showed weak or no staining." (PMID 35740573, 2022).
cancer (93 papers, 2012 to 2026). A tumor composed of atypical neoplastic, often pleomorphic cells that invade other tissues. "As an important splicing factor, SRSF3 has profound functions in health and its aberrant expression has been associated with progression of many diseases and cancer." (PMID 40568073, 2025). "The increased expression of SRSF3 in cancer cells is essential for cancer cell proliferation and loss of SRSF3 expression leads to cell apoptosis and senescence, and genome instability." (PMID 40568073, 2025). "The dysregulation of SRSF3, leading to the altered splicing of specific genes, has been linked to many human disorders such as cancer, neurological disorders, and inflammatory diseases." (PMID 38921043, 2024). "The high expression level of SRSF3 was associated to worse OS and death-specific survival among pan-cancer types." (PMID 35494088, 2022). "Previous researches have shown that SRSF3 expression was associated with cancer progression and correlated significantly with worse survival and shorter disease-free survival." (PMID 35494088, 2022). "SRSF3-regulated aberrant splicing is usually associated with numerous aspects of human cancers, such as the cell cycle, cytoskeleton, cell proliferation, apoptosis and other functions." (PMID 35198444, 2022). "Previous studies have shown that SRSF3 deficiency inhibits cancer cell proliferation, migration, invasion, and metastasis." (PMID 36344491, 2022). "Even though our results provided useful information of the association of SRSF3 expression level with tumorigenesis and regulation of the immune environment in cancers and additionally the OS, some limitations existed in this study." (PMID 35494088, 2022). "Clinical features, cell functions and related genes associated with upregulation of SRSF3 in human cancer." (PMID 33072610, 2020). "SRSF3 overexpression in cancer cells has a positive association with the steady status maintenance of ILF3 isoform-1 and−2, which can promote cell proliferation and transformation." (PMID 33072610, 2020). "The increased expression of SRSF3 overexpression in cancer cells causes the improvement of cell cycle performance by influencing the expression levels of G2/M transition regulators, including Forkhead box transcription factor M1 (FoxM1), PLK1, and Cdc25B." (PMID 33072610, 2020). "SRSF3 downregulation is associated with cell death by the treatment of caffeine, digoxin, theophylline, amiodarone, and amiloride in cancer cells." (PMID 33072610, 2020). "It is reported that SRSF3 is frequently overexpressed in most types of cancer and implicated in poor prognosis of cancer patients." (PMID 32308565, 2020). "We emphasize the negative consequences of the overexpression of the SRSF3 oncogene in cancers, the pathways underlying SRSF3-mediated transformation, and implications of potential anticancer drugs by downregulation of SRSF3 expression for cancer therapy." (PMID 33072610, 2020). "It has also been reported that higher expression of SRSF3 and the consequent splicing dysfunction is associated with neurodegenerative diseases and cancers." (PMID 30835716, 2019). "By investigating the oncogenic function of SRSF3, we previously observed that SRSF3 regulates a wide range of genes associated with cancer progression." (PMID 28039456, 2017). "Although it is implicated in the malignant phenotypes of various cancer cells, the molecular mechanism underlying SRSF3-mediated cancer progression is still obscure." (PMID 28039456, 2017). "SRSF3 is frequently upregulated in most types of cancer and is closely associated with the prognosis of cancer patients." (PMID 28039456, 2017). "Caffeine-induced serine/arginine-rich splicing factor 2, SRSF2, and SRSF3 are required for the alternative splicing of a subset of cancer-associated genes." (PMID 29254178, 2017).
cancer (continued). "In conclusion, our results suggest that the SRSF3/miR-1908-5p/NKIRAS2 axis is closely associated with the oncogenic functions of SRSF3 and is a promising target for cancer treatment." (PMID 28039456, 2017). "Loss of SRSF3 expression in a number of cancer cell lines increases apoptosis and decreases proliferation, and increased expression of SRSF3 leads to transformation of rodent fibroblasts and enables them to form tumours in nude mice." (PMID 23935626, 2013). "SRSF3, an RNA-binding serine/arginine-rich splicing factor 3, has been reported to be an oncogenic factor that is highly expressed and associated with poor prognosis in various types of cancer." (PMID 40568080, 2025). "However, the dysfunctional expression or improper regulation of SRSF3 has been associated with several diseases, including cancer and neurological and cardiac disorders." (PMID 38921043, 2024). "SRSF3 overexpression is strongly positively associated with various cancers." (PMID 37416784, 2023). "SRSF3 deficiency inhibits cancer cell proliferation, migration, and invasion." (PMID 36344491, 2022). "SRSF3 presents a gradual expression loss during cancer progression." (PMID 33072610, 2020). "Notably, the chromosome region bearing the SRSF3 locus on chromosome 6p is commonly amplified in cancer, thus causing aberrant SRSF3 overexpression." (PMID 32023846, 2020). "Ser/Arg-rich splicing factor 3 (SRSF3) is the smallest member of the SR protein family, and its level is controlled by multiple factors and involves complex mechanisms in eukaryote cells, whereas the aberrant expression of SRSF3 is associated with many human diseases, including cancer." (PMID 33072610, 2020). "In addition, aberrant mutations of SF3B1 in a gain-of-function form and high expression of SRSF3 are commonly associated with some types of cancers." (PMID 33086735, 2020). "Several studies have previously implicated hnRNPM and SRSF3 in human cancers." (PMID 32023846, 2020). "Similar to other SR members, SRSF3-related aberrant splicing is often associated with the non-sense-mediated mRNA decay pathway, resulting in inducing aberrant protein isoforms that are often linked to numerous human diseases, including cancers." (PMID 33072610, 2020). "Increased expression of the SR protein SRSF3 is also associated with cancer." (PMID 23935626, 2013). "Although restoring a proper expression level of SRSF3 in specific cells may be the key for curing SRSF3 deficiency-induced diseases, blocking SRSF3 expression and its functions in cancer cells by small molecules will be an exciting and promising roadmap for future cancer therapies." (PMID 37416784, 2023). "Interestingly, SRSF3 expression was also linked to upregulation of certain specific immune checkpoint genes among different cancer types, such as KICH, LIHC, and SRSF3, which may result in immune cells differentiation and polarization." (PMID 35494088, 2022). "In addition, SRSF3 or other SR proteins are known to associate with various cancers." (PMID 35563766, 2022). "CircRNAs are generated through back-splicing mechanisms, with SRSF3 playing a pivotal role in their biogenesis in other cancers." (PMID 41303368, 2025). "On the other hand, PTBP1 impairs SRSF3 autoregulation which likely explains the overexpression of both in primary cancers which predominantly express RIF1-S." (PMID 41489901, 2025). "This study, for the first time in NSCLC cells including those without a targetable TK mutation, explores a tumor-suppressive activity of siRNA knockdown of a splicing factor SRSF3, which was reportedly effective in other cancer cell types." (PMID 40568080, 2025). "The serine/arginine-rich splicing factor 3 (SRSF3) has been shown to play a role in this process in other cancers." (PMID 41303368, 2025).
cancer (continued). "Exposure to DNA damage inhibited Ex32 splice-in, potentiated the association of SRSF3 and SRSF7 with RIF1 pre-mRNA, and caused an increase in RIF1-S protein expression, which was also observed across a diverse set of primary cancers." (PMID 41489901, 2025). "SRSF3 was initially discovered as a proto-oncogene responsible for cell proliferation overexpressed in various types of cancers for cancer cell proliferation and tumor maintenance." (PMID 40568073, 2025). "Our findings provide new insights into the characteristics of full-length and truncated SRSF3 proteins in cancer cells." (PMID 38909100, 2024). "SRSF3 plays a role in a wide array of complex biological processes and is involved in cancer, aging, and neurological and cardiac disorders." (PMID 38909100, 2024). "Given the fact that SRSF3 is overexpressed in multiple cancers, including OSCC and acts as an oncogene, we decided to investigate how miR-6741-3p-mediated regulation of SRSF3 affects its oncogenic function in OSCC cells in vitro and in vivo." (PMID 38781195, 2024). "Gene amplification and impairment of SRSF3 autoregulation have been attributed to its overexpression in at least a subset of these cancers." (PMID 38781195, 2024). "Splicing factors, such as CUGBP1, hnRNP proteins, SF2/ASF, and SRp20/SRSF3, have been reported to contribute to the dysregulation of the IR-A: IR-B ratio in cancer." (PMID 38331804, 2024). "As a proto-oncogene, SRSF3 is crucial in cellular proliferation, tumorigenesis, and cancer maintenance." (PMID 38216996, 2024). "This is in line with other studies where the overexpression of SRSF3 promoted proliferation and anchorage-independent growth of cancer cells, while the knockdown of SRSF3 suppressed proliferation and anchorage-independent growth." (PMID 38781195, 2024). "We show here that Serine‐arginine rich splicing factor 3 (SRSF3) controls the processing of miR‐17‐92 cluster miRNAs in pluripotent and cancer cells." (PMID 37306233, 2023). "Knockdown of SRSF3 significantly decreases lactate production and cancer cell proliferation by decreasing exon 10 inclusion which is independently of exon 9 inclusion." (PMID 37416784, 2023). "The preferential SRSF3‐mediated processing of the paralogs miR‐17 and miR‐20a led to enhanced cell cycle progression and proliferation in both mouse pluripotent and human cancer cells through the regulation of the cell cycle inhibitor CDKN1A/p21." (PMID 37306233, 2023). "Consistently, previous studies have identified SRSF3 as a proto-oncogene with high expression in various cancers." (PMID 37558679, 2023). "SRSF3 overexpression is partially resulted from the reduced inclusion of its poison exon 4 and the impaired autoregulation in cancers." (PMID 37416784, 2023). "Increased SRSF3 expression is necessary for indefinite growth of cancer cells and prevents cancer cell apoptosis." (PMID 37416784, 2023). "Following our observation, many other studies including ours have explored the expression, functions and regulatory mechanisms of SRSF3 in various cancers." (PMID 37416784, 2023). "SRSF3 acts as an inhibitory regulator of SF3B4 that affects the activity and function of dendritic cells via the SRSF3-pyruvate kinase M2 pathway, which is crucial for cancer cell migration and immune killing." (PMID 37899451, 2023). "Theophylline and amiodarone downregulate SRSF3 expression and exert anticancer activity in cancer cell lines." (PMID 36764525, 2023). "SRSF3 is a member of the SR family that has been identified as an oncogene and is frequently overexpressed in many types of cancers, including HNSCC." (PMID 36835286, 2023). "In contrast, depletion of SRSF3 in many types of cancer cells examined inhibits cell proliferation and induce cell apoptosis initially found in U2OS cells." (PMID 37416784, 2023). "SRSF3 enhances cell proliferation during somatic reprogramming and in pluripotent cells similar to that observed in various human cancer cell lines." (PMID 37306233, 2023).